IL6 (interleukin 6)
Diseases named in the same sentence as IL6 in open-access papers (continued):
Sharing a sentence is not in itself a finding about the gene and the disease.
periodontitis (continued). "In addition, TNF-α and IL-6 levels are higher in alcohol users, which might be equally in crevicular fluid, being related to the presence of periodontitis." (PMID 32730269, 2020). "Therefore, we aimed to test the hypothesis that LPS-induced periodontitis could contribute to peripheral changes of inflammatory biomarkers (IL-6, IL-10, PTX3, and sTWEAK) in rats." (PMID 31583485, 2020). "The high prevalence of periodontitis, as well as the high risk of mortality from CAD and a scarcity of studies in this area led to the study of the association between periodontitis and coronary artery disease, by assessing the presence of PCR and IL-6 polymorphisms." (PMID 32215496, 2020). "Also, salivary macrophage inflammatory protein-1α, matrix metalloproteinase-8, interleukin- (IL-) 1β, IL-6, prostaglandin E2, and tumor necrosis factor- (TNF-) α levels seem to be associated with gingivitis and periodontitis, having a high potential to be used in their diagnosis." (PMID 30906485, 2019). "Although evidence directly tying periodontitis to systemic disease via increased circulating cytokines is lacking, some studies, both clinical and pre-clinical, have reported that periodontitis-induced increases in serum IL-6 and CRP levels can lead to endothelial dysfunction." (PMID 31293577, 2019). "Therefore, we can conclude that the salivary level of IL-6 and IL-17 may help in the subcategorization of periodontitis." (PMID 29670909, 2018). "Periodontitis (gum problems) and dental caries, two aspects of poor oral health, may play a role in sports injuries because of their association with elevated levels of pro-inflammatory cytokines, like tumour necrosis factor (TNF-a) and interleukin-6 (IL-6)." (PMID 30377533, 2018). "Thus, oral bacteria and their components may directly stimulate IL-6 production by periodontal ligament fibroblasts during periodontitis." (PMID 29453398, 2018). "Association of SNPs in vascular endothelial growth factor (VEGF), IL-6, IL-10, IL-1beta, interferon alpha, TNF-alpha genes with immunoregulatory function revealed that C allele of VEGF, an allele of IL-10 and GG genotype of TNF-alpha, was individually associated with chronic periodontitis." (PMID 29489938, 2018). "Thus, higher salivary concentrations of IL-6 observed in patients with periodontitis may be related to other factors than the genetic influence, especially environmental risk factors, such as bacterial load or poor oral hygiene habits." (PMID 25548674, 2014). "Interestingly, all three studied patient groups (gingival health, gingivitis and chronic periodontitis) exhibited a similar average of IL-6 positive cells in the gingival biopsies, while COX-2 expression was significantly associated with periodontal disease severity." (PMID 24551049, 2014). "Therefore, we believe that the observed higher levels of IL-6 in saliva of patients with periodontitis may be related to other factors prevalent to the analyzed polymorphism." (PMID 25548674, 2014). "Indeed, the data of the present study do not show any association between CRP, IL-6, leptin or adiponectin with periodontitis in morbidly obese patients." (PMID 23526947, 2013). "In this regard the decreased expression of pro-inflammatory genes like IL-1 and IL-6 that have been demonstrated to be over-expressed in untreated periodontitis sites may indicate a strong down-regulation of the pro-inflammatory immune response induced by periodontal treatment." (PMID 18606014, 2008). "The results indicate that EVO exhibits potent antimicrobial activity against key periodontal pathogens and suppresses pathogen-induced ROS generation as well as the release of pro-inflammatory cytokines (IL-1β, IL-6, TNF-α) under periodontitis conditions." (PMID 42072113, 2026). "Others, however, found significant differences of many markers between serum from periodontitis patients and controls, among them MCP‐1 and IL‐6." (PMID 41580300, 2026).
periodontitis (continued). ", significantly attenuates key pro-inflammatory cytokines (IL-6, IL-1β, and TNF-α) at both the mRNA and protein levels in a rat periodontitis model." (PMID 41484074, 2026). "Periodontitis patients before and 1 year present with similar levels of MCP‐1, TNF‐α, and IL‐6, cytokine equilibrium." (PMID 41580300, 2026). "Periodontitis elevates circulating pro-inflammatory cytokines (e.g. TNF-α, IL-1β, IL-6), which can cross the blood–brain barrier, activate microglia and promote neuroinflammation—a process implicated in amyloid-beta accumulation and tau pathology." (PMID 41406907, 2026). "In the present study, MKE significantly decreased the levels of key inflammatory mediators such as iNOS, TNF-α, IL-6, IL-1β, COX-2, and mPGES-1 in the periodontitis-induced rat model." (PMID 41614939, 2026). "Several pro-inflammatory cytokines, including IL-1, IL-6, IL-12, IL-17, IL-18, IL-21, TNF-α, and IFN-γ, play a critical role in the pathogenesis of periodontitis." (PMID 40136726, 2025). "Systemically, periodontitis induces inflammation as evidenced by elevated serum IL-6 and TNF-α levels in periodontitis mice." (PMID 41040884, 2025). "This study provides a comprehensive analysis of key inflammatory biomarkers (CRP, IL-1, IL-6, TNF-α) across all stages and grades of periodontitis, offering detailed insights into both systemic and local inflammatory responses." (PMID 41440349, 2025). "We found that UA reduced IL-6 and TNF-α levels in vitro and in vivo, inhibited osteoclast differentiation, and decreased the RANKL/OPG ratio in periodontitis mice." (PMID 40649395, 2025). "Elevated levels of IL-6 have been consistently observed in the gingival crevicular fluid (GCF) and gingival tissues of periodontitis patients compared to healthy individuals." (PMID 40136726, 2025). "In the first part of the study, we examined the effect of adiponectin on the expression in periodontal ligament cells of mRNA of mediators involved in periodontitis pathogenesis (TNF-α, IL-1, IL-6, IL-8, IL-10, IL-17, IL-18)." (PMID 40282186, 2025). "Patients with severe periodontitis exhibit significantly elevated levels of pro-inflammatory mediators—namely IL-1β, TNF-α, and IL-6—in both serum and saliva." (PMID 40869031, 2025). "Both IL6/JAK/STAT3 and TGF-β1/SMAD pathways play crucial roles in the inflammatory and fibrotic responses in periodontitis and renal pathology." (PMID 40452929, 2025). "Both RA and periodontitis are driven by elevated levels of pro-inflammatory cytokines, such as TNF-α, IL-1, and IL-6, which promote tissue destruction in the joints and periodontium." (PMID 40066344, 2025). "Key periodontitis-related mediators involved in AD pathogenesis are cathepsin B, gingipain, LPS, TNF, and IL-6." (PMID 40559320, 2025). "More studies are needed to investigate the role of other inflammatory cytokines (besides IL-1β), such as TNF-α, IL-6, RANKL, and OPG, in the inflammatory reaction of induced periodontitis and subsequent alveolar bone resorption." (PMID 40692535, 2025). "C-reactive protein (CRP), an acute-phase reactant produced primarily in the liver in response to inflammatory cytokines like IL-6, is elevated in both CVD and periodontitis." (PMID 40136726, 2025). "In periodontitis, it can be also released by periodontal ligament fibroblasts, T and B cells under pro-inflammatory stimuli (e.g. TNF-α, IL-1β, and IL-6) in the presence of LPS." (PMID 40736688, 2025). "In the current study, as periodontitis was induced, a significant increase in the production of pro-inflammatory cytokines TNF-α and IL-6 was observed." (PMID 40007939, 2025). "IL-1β, IL-6, IL-17, IL-23, and TNF are well documented in periodontitis, having various roles in immune cell recruitment, pro-inflammatory activity, and periodontal tissue destruction." (PMID 41463036, 2025).
periodontitis (continued). "Within the limitations of this retrospective study, non-surgical periodontal therapy was associated with significant reductions in systemic inflammatory biomarkers (CRP, IL-1β, IL-6, TNF-α) across all stages and grades of periodontitis." (PMID 41440349, 2025). "IL-6 and irisin levels were significantly elevated in individuals with Stage III Grade C periodontitis compared to periodontally healthy participants." (PMID 41007333, 2025). "Consistent with existing literature 45-47, periodontitis was found to elevate levels of various growth factors and inflammatory mediators, including G-CSF, IFN-γ, IFN-I, IL-1α, IL-6, and TNF-α." (PMID 40521205, 2025). "In saliva, IL-1β and IL-6 were significantly elevated in T1DM patients, especially those with periodontitis (p < 0.001), with IL-1β also distinguishing T1DM individuals with gingivitis (p < 0.05)." (PMID 41280935, 2025). "Increased IL-1β, IL-6, and TNF-α levels were also found in patients with periodontitis and AD suggesting the presence of overlapping mechanisms in the physiopathology of these diseases." (PMID 40736688, 2025). "Peptostreptococcus in periodontitis can stimulate various immune cells and produce TNF-α, IL-6, or IL-1β to trigger an inflammatory response, promoting bone resorption and causing irreversible destruction of the periodontium." (PMID 40387401, 2025). "This study provides valuable insights into the relationship between periodontitis and CKD by evaluating IL-6 and TGF-β, two key cytokines involved in inflammatory and fibrotic pathways." (PMID 40452929, 2025). "While IL1A, IL1B, IL6, and TNFA are among the most extensively studied cytokine genes in periodontitis, numerous other pro- and anti-inflammatory mediators have been implicated in disease susceptibility, progression, and tissue destruction." (PMID 41300760, 2025). "The current study explored the outcomes of NSPT in modulating periodontal parameters, renal function, and concentration of inflammatory biomarkers (IL-6, and TGF-β1) in CKD patients with periodontitis." (PMID 40452929, 2025). "And periodontitis disease progression was inhibited by reducing M1 macrophage polarization and decreasing the iNOS, TNF-α, and IL-6 expression." (PMID 40032778, 2025). "The synergistic impact of elevated pro-inflammatory cytokines (TNF-α, IL-6, and resistin) and reduced APN disrupts insulin signaling pathways, thereby affecting periodontitis." (PMID 41246338, 2025). "Numerous studies have confirmed that individuals with periodontitis exhibit higher serum levels of inflammatory markers such as IL-1β, TNF-α, IL-17A, IL-6, and lower levels of the anti-inflammatory cytokine IL-10 compared to healthy controls." (PMID 40732209, 2025). "Lipopolysaccharides and other byproducts from periodontitis elevate cerebral pro-inflammatory mediators (IL-1β, TNF-α, IL-6), which promote amyloid accumulation, leading to neurodegeneration and Alzheimer’s disease." (PMID 40433667, 2025). "In periodontitis, producing pro-inflammatory cytokines such as TNF-α, IL-1, IL-6, and IL-17 contributes to chronic inflammation, tissue degradation, and bone resorption." (PMID 40136728, 2025). "Their results showed that after periodontitis treatment in hypertensive patients, the indices of pro-inflammatory cytokines TNF-α and IL-6 decreased and were within normal limits." (PMID 40002786, 2025). "Specifically, the persistent inflammatory response in periodontitis leads to the activation of immune cells, which secrete a wide array of pro-inflammatory cytokines, such as TNF-α, IL-1β, and IL-6." (PMID 39987090, 2025). "When all individuals (healthy + periodontitis) were evaluated together, age, PI, PD, BOP, and CAL exhibited significant and strong positive correlations with both IL-6 and irisin levels (p < 0.001)." (PMID 41007333, 2025).
periodontitis (continued). "Multiple studies have also observed signs of systemic inflammation in HD patients with periodontitis, with elevated levels of CRP, amongst other inflammatory biomarkers such as IL‐6 and IL‐8." (PMID 41476846, 2025). "Therefore, IL-6 may be involved critically in the pathological process of periodontitis." (PMID 40649395, 2025). "This led to the following research question: What is the effect of closed-field scaling and root planning on serum levels of IL-1β, IL-4, IL-6, IL-8, IL-10, IL-12p70, IL-17A, VEGF, and TNF-α in patients with periodontitis and high blood pressure?" (PMID 40002786, 2025). "Vaspin, a serine protease inhibitor, shows significantly elevated levels in obese patients with periodontitis, correlating with changes in inflammatory factors like TNF-α and IL-6." (PMID 41246338, 2025). "In the rat model of ligature-induced periodontitis, expression levels of the proinflammatory cytokines TNF-α, IL-1β, and IL-6 in gingival tissue were significantly reduced in the E1 and E2 groups compared with those in the PC group." (PMID 40808155, 2025). "Arecent study examined the correlation of LRG in periodontitis by analysing GCF and blood concentrations of LRG, IL-6, and TNF-α inindividual with stage-3 periodontitis." (PMID 40822769, 2025). "Elevated gingival crevicular fluid (GCF) levels of IL-6, IL-17, and IL-35 have been reported in patients with Stage III–IV periodontitis compared with healthy controls, with IL-17 showing a strong correlation with probing depth." (PMID 41440349, 2025). "We propose that this subgroup of fibroblasts can directly promote the progression of periodontitis by secreting SASP-related factors, such as IL-6, and indirectly amplify inflammation by recruiting neutrophils through the complement pathway, specifically C3." (PMID 40801798, 2025). "Periodontitis patients showed an elevated leukocyte count, TNF-α, IL-8, IL-6, and active MMP-8 (aMMP-8) level, posing a threat to endothelial dysfunction and contributing to the incidence of atherosclerosis." (PMID 41552724, 2025). "This IL-6 –RANKL–osteoclast axis accelerates alveolar bone resorption, which represents a key pathological feature of periodontitis." (PMID 41007333, 2025). "In the process of periodontitis, chemokines such as CXCL-8, CXCL-1, and CCL-5 and cytokines such as TNF-α, IL-1β, and IL-6 are present, due to the action of these multi-factors, it progresses to severe periodontitis with loss of periodontal support structures." (PMID 40733170, 2025). "The results showed that PA significantly reduced IL-1β, IL-6, TNF-α, CRP, and LPO levels and increased IL-10 levels in the periodontitis group; moreover, the histological analysis showed reduced inflammatory infiltrate and less fiber degradation." (PMID 40422620, 2025). "The results revealed that the expression of NLRP3, IL‐1β, IL‐18, IL‐6, and TNF‐α was upregulated by F. nucleatum and its OMVs in rats with periodontitis." (PMID 39475060, 2024). "Based on previously published data, IL-1β, IL-6 and TNF-α were chosen, in order to mimic the inflammatory environment that can be found in periodontitis." (PMID 39252697, 2024). "The body responds to periodontitis by producing inflammatory cytokines like TNF-α, IL-1β, and IL-6, which play crucial roles in the disease's progression." (PMID 39044527, 2024). "qRT-PCR results indicated that mRNA levels of the pro-inflammatory cytokines (IL-1, IL-6, and IL-8) and also CFI, DDIT4L, F4AM6C were upregulated in patients with periodontitis compared with healthy controls." (PMID 38218802, 2024). "Extensive research has explored the connections between periodontitis and various blood cell components, including ESR, CRP, IL-6, fibrinogen, Von Willebrand factor, and thrombocytes." (PMID 38595889, 2024). "They concluded that an upsurge of pro-inflammatory interleukins i.e. interleukin-1 alpha (IL-1α), IL-1β, interleukin-12 (IL-12), and IL-6 along with TNF-α, found in periodontitis." (PMID 38196480, 2024).
periodontitis (continued). "Plasma levels of TNF-α and PGE2 were found to be elevated in women with periodontitis compared to periodontally healthy women, while pregnant women with periodontitis showed elevated plasma levels of TNF-α, IL-4, and IL-6." (PMID 38672972, 2024). "Pro‐inflammatory cytokines, such as interleukin (IL)‐6, IL‐1β, and tumor necrosis factor (TNF)‐α, have been identified as the key molecules leading to the development of periodontitis." (PMID 38656694, 2024). "Elevated levels of pro-inflammatory cytokines, such as interleukin-6 (IL-6), IL-17A, and IL-33, have been detected in the saliva of SLE patients with chronic periodontitis." (PMID 39338471, 2024). "The reduction of IL-1β, TNF-α, IL-6, and RANKL levels after dietary supplementation with n-3 PUFA as an adjunctive therapy for periodontitis was the most prevalent among the reviewed studies." (PMID 39661860, 2024). "A more comprehensive evaluation of additional combinations of periodontitis biomarkers, beyond MMP-8 with IL-1β and IL-6, is warranted, along with the development of more sensitive biomarker assays." (PMID 39554809, 2024). "Specifically, IL-1β, TNF-α, IL-6, and RANKL levels were reduced after dietary supplementation with n-3 PUFA as an adjunctive therapy for periodontitis." (PMID 39661860, 2024). "Cytokines, such as IL-1β, IL-6 and TNF-α, activate inflammation-related transcription factors or activate related signaling pathways, thereby accelerating the process of periodontitis." (PMID 38178140, 2024). "It has been well documented that NF-kB activation, which is pivotal in periodontitis and cancer-related inflammation, induces the expressions of pro-inflammatory cytokines, including TNF-α, IL-1β, IL-6, and IL-8, in different cell types." (PMID 38612423, 2024). "The explanation for the relationship is that periodontitis can activate cascades of inflammatory immune mediators, such as prostaglandin E2 (PGE2), IL-6, IL-1, and TNF-alpha, and thus be related to adverse perinatal outcomes." (PMID 38397649, 2024). "This study's main objective was to compare the concentrations of IL-6, IL-17, and IL-35 in the GCF of individuals with Stage III and IV periodontitis and healthy controls." (PMID 39215253, 2024). "The quantification of the level of these inflammatory mediators in the gingival crevicular fluid (GCF) suggests that IL-6, interleukin-8 (IL-8), and TNF-α have been reported as relevant biomarkers in the pathophysiology of periodontitis." (PMID 38196480, 2024). "This study compared the concentrations of interleukin (IL)-6, IL-17, and IL-35 in the gingival crevicular fluid of periodontally healthy participants with individuals who had stage III and IV periodontitis." (PMID 39215253, 2024). "This study evaluated changes in inflammatory markers within GCF, including TNF-α, IL-1β, IL-6, IL-8, hs-CRP, ICAM-1, HMGB1, and PGE2, before and after treatment in patients with osteoporosis and periodontitis." (PMID 39686428, 2024). "The present study aimed to assess the clinico-radiographic parameters and salivary levels of RANKL, OPG, IL-6, and TNF-α around standard implant- and SDI-supported fixed partial dentures in partially dentate T2DM patients treated for periodontitis." (PMID 39625348, 2024). "Moderate certainty evidence shows that NSPT has a positive effect on the reduction of IL-6 and SBP in patients with periodontitis, while low certainty evidence shows that NSPT is effective for reduction of CRP." (PMID 38877442, 2024). "Another study found that chemerin and inflammatory cytokines such as IL‐1β, IL‐6, and TNF‐α were notably higher in the serum of patients with chronic periodontitis than those in the control group, (periodontally healthy/gingivitis)." (PMID 39494478, 2024). "The findings suggested that MBG did not have an impact on the expression of inflammatory genes (IL-1β, IL-6, iNOS and TNF-α) that were activated in the periodontitis microenvironment." (PMID 38449005, 2024).